FOXD2 (forkhead box D2)
Description:
Probable transcription factor involved in embryogenesis and somatogenesis.
Synonyms: FREAC-9; FKHL17; FREAC9
Tractability: No criterion of Open Targets' tractability assessment is met for any kind of drug.
Gene: Protein-coding gene on chromosome 1 (47,438,044 to 47,440,691, forward strand). Ensembl gene ENSG00000186564.
Subcellular location: Nucleus
Gene Ontology:
Molecular function: DNA-binding transcription activator activity, RNA polymerase II-specific; protein binding; sequence-specific DNA binding; sequence-specific double-stranded DNA binding; DNA-binding transcription factor activity; DNA-binding transcription factor activity, RNA polymerase II-specific; RNA polymerase II cis-regulatory region sequence-specific DNA binding
Biological process: positive regulation of transcription by RNA polymerase II; anatomical structure morphogenesis; cell differentiation; regulation of transcription by RNA polymerase II; regulation of DNA-templated transcription
Cellular component: chromatin; nucleus
Genetic constraint (gnomAD): Loss-of-function variants: 4 observed, 1.88 expected, observed/expected ratio (o/e) 2.13. That is too few expected variants to judge how well the gene tolerates losing a copy. Missense variants: 678 observed, 561 expected, observed/expected ratio (o/e) 1.21, 90% interval 1.13 to 1.29. Synonymous variants: 373 observed, 286 expected, observed/expected ratio (o/e) 1.3, 90% interval 1.2 to 1.42.
Homologues: Orthologues: chimpanzee FOXD2 (99% identical), macaque FOXD2 (97% identical), dog FOXD2 (95% identical), guinea pig FOXD2 (94% identical), mouse Foxd2 (93% identical), rat Foxd2 (93% identical), pig FOXD2 (92% identical), tropical clawed frog foxd2 (41% identical), Drosophila melanogaster fd59A (27% identical). Paralogues in human: FOXD1 (46% identical), FOXD3 (35% identical), FOXD4L1 (28% identical), FOXD4 (27% identical), FOXD4L4 (26% identical), FOXD4L5 (26% identical), FOXD4L6 (26% identical), FOXD4L3 (26% identical), FOXC2 (22% identical), FOXC1 (21% identical), FOXE3 (21% identical), FOXB1 (21% identical), and 29 more.
Diseases named in the same sentence as FOXD2 in open-access papers:
FOXD2 is named in the same sentence as 21 diseases in open-access papers, as found by Europe PMC text mining. Sharing a sentence is not in itself a finding about the gene and the disease. The quoted sentences say what the papers report.
colon carcinoma (3 papers, 2012 to 2025). "Indeed, 6 out of 10 leading TFs have direct evidence and some experimental validation of their involvement in colon cancer risk and progression: ZNF334, FOXD2, FOXD3, POU3F3, NR1H4, and VSX2." (PMID 41114645, 2025). "Moreover, external validation with the TCGA database was also successful showing that MSI-H expressed less FOXD2 than MSI-L/MSS colon carcinomas (p = 0.001)." (PMID 26388956, 2015).
meningioma (2 papers, 2015 to 2024). A generally slow growing tumor attached to the dura mater. "Noteworthy, the only two studies of FOXD2 in humans are related to cancer; in one, a locus including the FOXD2 was found to be deleted in meningioma and, in the other, the protein was found to be more highly expressed in prostate cancer and lymph node metastases compared to normal prostate." (PMID 26388956, 2015).
brain malformations (1 paper, 2024). "Haploinsufficiency of NFIA has been associated with brain malformations and CAKUT, and upregulation could be a compensatory mechanism in Foxd2 KO cells." (PMID 38154558, 2024).
Cirrhosis (1 paper, 2019). A chronic disorder of the liver in which liver tissue becomes scarred and is partially replaced by regenerative nodules and fibrotic tissue resulting in loss of liver function. "In addition, we also found that MED24, FOXD2 and ZNF282 are associated with the progression from cirrhosis to HCC." (PMID 31811111, 2019).
head and neck cancer (1 paper, 2020). A primary or metastatic malignant neoplasm affecting the head and neck. "We further analyzed the transcriptional profile of FOXD1, FOXD2 and FOXD4 in the anatomic subdivision of TCGA head and neck cancer and found that the expression of FOXD2 in the hypopharynx and FOXD4 in the tonsil is relatively higher than other tissues, such as the oral cavity." (PMID 32967107, 2020). "We next evaluated the prognostic significance of FOXD1, FOXD2, FOXD3 and FOXD4 in TCGA head and neck cancer patients." (PMID 32967107, 2020). "Kaplan–Meier analysis revealed that FOXD1, as compared to FOXD2, FOXD3 and FOXD4, upregulation more significantly (p = 0.008) predicts a poor overall survival rate in TCGA head and neck cancer patients." (PMID 32967107, 2020). "Moreover, except FOXD3, we found that FOXD1, FOXD2 and FOXD4 are more significantly (p < 0.01) upregulated in primary tumor tissue compared to normal adjacent tissues derived from TCGA head and neck cancer patients." (PMID 32967107, 2020).
kidney failure (1 paper, 2024). An acute or chronic condition that is characterized by the inability of the kidneys to adequately filter the blood. "Of note, in contrast to Foxd2 mutant mice, homozygous Foxd1 KO mice die shortly after birth of kidney failure due to hypoplastic kidneys." (PMID 38154558, 2024).
lymphoma (1 paper, 2019). A malignant (clonal) proliferation of B- lymphocytes or T- lymphocytes which involves the lymph nodes, bone marrow and/or extranodal sites. "Also, the mutation effects on TF binding at the promoter of two important FL genes (BCL6 and BCL2) were recovered: for example, regulatory activities of two TFs (FOXD2 and FOXD3) on BCL6 and BCL2 were confirmed previously by knockdown experiments in SUDHL4 lymphoma cell." (PMID 31001324, 2019).
Multiple Myeloma (1 paper, 2024). "DeepIMAGER was applied to scRNA-seq datasets of multiple myeloma (MM) and detected potential GRNs for TFs of RORC, MITF, and FOXD2 in MM dendritic cells." (PMID 39062480, 2024). "When applied to scRNA-seq datasets of Multiple Myeloma (MM) patients, we identified potential regulations in GRNs of three TFs, RORC, MITF, and FOXD2 in dendritic cells, including many known regulations related to MM pathology." (PMID 39062480, 2024).
oral cancer (1 paper, 2020). "Robustly, FOXD1, but not FOXD2, FOXD3 and FOXD4, was significantly (p < 0.01) upregulated in primary tumors compared to normal adjacent tissues derived from oral cancer patients deposited in the GSE42743 dataset." (PMID 32967107, 2020).
renal hypoplasia (1 paper, 2024). Renal hypoplasia is a developmental anomaly in which one or both kidneys (unilateral or bilateral renal hypoplasia, respectively) have a deficit in the number of nephrons and may be small. "Here, we report the identification of a homozygous frameshift variant and 2 homozygous missense variants in FOXD2 in 3 unrelated families implicated in autosomal recessive syndromic CAKUT with renal hypoplasia, facial dysmorphies, and proteinuria." (PMID 38154558, 2024).
cancer (8 papers, 2014 to 2024). A tumor composed of atypical neoplastic, often pleomorphic cells that invade other tissues. "For example, in thyroid carcinoma, lncRNA FOXD2 adjacent opposite strand RNA 1(FOXD2-AS1) promotes the cancer stem cell features and anoikis resistance in thyroid cancer cells via inhibiting the miR-7-5p/telomerase reverse transcriptase (TERT) axis." (PMID 31744046, 2019). "In addition, FOXD2 and FOXM1 belong to the forkhead box (FOX) proteins, and FOX deregulation is known to be associated with many diseases, particularly for FOXM1, which is an oncogene that is overexpressed in most types of human cancer." (PMID 31561539, 2019). "Additionally, we also identified several genes, including FOXS1, FOXP3, and FOXD2, showed elevated expression in a variety of tumors, while FOXF1, FOXP2, and FOXO1 were downregulated in the majority of cancers." (PMID 37401400, 2023).
tumor (6 papers, 2015 to 2024). "Whether FOXD2 could be acting as a tumour suppressor gene in MSI-H CRC deserves future studies." (PMID 26388956, 2015). "In the colon, binding of FOXD2 to compacted chromatin facilitates recruitment of KMT2D and rewiring enhancer through deposition of H3K4me1, which functions as a tumor suppressor." (PMID 39117610, 2024). "The long noncoding RNA (lncRNA) Forkhead box D2 (FOXD2) adjacent opposite strand RNA 1 (FOXD2-AS1) is overexpressed in glioma tumors and correlates positively with tumor grade." (PMID 32906592, 2020). "According to these results, the expression levels of NR3C2, KLF4, CASZ1, FOXD2, ATOH1, and RORC reduce in CRC and may function as tumor suppressors." (PMID 36344988, 2022).
FOXD2 also shares sentences with these, for which no sentence is quoted: breast carcinoma (1 paper); colorectal cancer (1); Hydroureter (1); Hypertension (1); kidney diseases (1); nephrotic syndrome (1); nervous system tumors (1); prostate carcinoma (1); renal fibrosis (1).